SERPINE3 (serpin family E member 3)
Description:
Probable serine protease inhibitor.
Tractability: Antibody: UniProt places it where antibodies can reach, with high confidence; UniProt predicts a signal peptide or a membrane-spanning region; its Gene Ontology location is reachable by antibodies, with medium confidence.
Gene: Protein-coding gene on chromosome 13 (51,335,773 to 51,364,735, forward strand). Ensembl gene ENSG00000253309.
Subcellular location: Secreted
Gene Ontology:
Molecular function: serine-type endopeptidase inhibitor activity
Cellular component: extracellular region
Genetic constraint (gnomAD): Loss-of-function variants: 32 observed, 29.63 expected, observed/expected ratio (o/e) 1.08, 90% interval 0.81 to 1.45. The upper end of that interval is the gene's LOEUF score, 1.45, which puts it in group 5 of 6, group 1 being the genes least tolerant of losing a copy. Missense variants: 346 observed, 414.77 expected, observed/expected ratio (o/e) 0.83, 90% interval 0.76 to 0.91. Synonymous variants: 170 observed, 169.1 expected, observed/expected ratio (o/e) 1.01, 90% interval 0.89 to 1.14.
Homologues: Orthologues: chimpanzee SERPINE3 (97% identical), macaque SERPINE3 (92% identical), rabbit SERPINE3 (76% identical), pig SERPINE3 (69% identical), guinea pig SERPINE3 (67% identical), rat Serpine3 (67% identical), mouse Serpine3 (66% identical), dog SERPINE3 (58% identical), tropical clawed frog SERPINE3 (47% identical), zebrafish serpine3 (42% identical). Paralogues in human: SERPINE1 (29% identical), SERPINE2 (29% identical), SERPINC1 (27% identical), SERPINB1 (26% identical), SERPINB8 (26% identical), SERPINB11 (25% identical), SERPINA9 (25% identical), SERPINA11 (25% identical), SERPINA3 (25% identical), SERPINB3 (25% identical), SERPINB9 (24% identical), SERPINB4 (24% identical), and 24 more.
Diseases named in the same sentence as SERPINE3 in open-access papers:
SERPINE3 is named in the same sentence as 11 diseases in open-access papers, as found by Europe PMC text mining. Sharing a sentence is not in itself a finding about the gene and the disease. The quoted sentences say what the papers report.
age-related macular degeneration (1 paper, 2022). Age-related loss of vision in the central portion of the retina (macula), secondary to retinal degeneration. "SERPINE3 is upregulated in human patients with age-related macular degeneration, a progressive eye disease that is linked to chronic inflammation and wound healing." (PMID 35727138, 2022).
Alzheimer disease (1 paper, 2026). A progressive, neurodegenerative disease characterized by loss of function and death of nerve cells in several areas of the brain leading to loss of cognitive function such as memory and language. "On a gene level, the most convincing finding was the SERPINE3 gene, which was close to MAGMA genome-wide significance for the Picture Sequence test and is thought to be involved in Alzheimer’s disease and prion diseases." (PMID 41535554, 2026).
cholangiocarcinoma (1 paper, 2023). A carcinoma that arises from the intrahepatic biliary tree (intrahepatic cholangiocarcinoma) or from the junction, or adjacent to the junction, of the right and left hepatic ducts (hilar cholangiocarcinoma). "The results shown that SERPINE1 was the highest expression in glioblastoma multiforme (GBM), SERPINE2 was the highest expression in kidney renal papillary cell carcinoma (KIRP), and SERPINE3 was the highest expression in cholangiocarcinoma (CHOL)." (PMID 38274096, 2023).
fetal growth restriction (1 paper, 2024). A fetus that does not grow beyond the 10th percentile of conventionally accepted weight for gestational age. "Placental mRNA expression was examined for the 8 genes enriched in isolated trophoblast side-population cells (CXLC8/IL8, ELL2, GATA6, HK2, HLA-DPB1, INTS6, SERPINE3, UPP1) in placentas obtained from participants with early onset preeclampsia (n = 78) or fetal growth restriction (n = 30)." (PMID 39028417, 2024).
cancer (2 papers, 2023 to 2025). A tumor composed of atypical neoplastic, often pleomorphic cells that invade other tissues. "In terms of TMB, SERPINE1, SERPINE2, and SERPINE3 were found to associated with TMB in seven cancers, fourteen cancers, and four cancers, respectively." (PMID 38274096, 2023). "Our results indicated that SERPINE1 was highly expressed, SERPINE2 was moderately expressed, and SERPINE3 was lowly expressed in pan-cancer." (PMID 38274096, 2023). "SERPINE3 is higher expressed in six cancer types and low expressed in seven cancers." (PMID 38274096, 2023). "The research of SERPINE3 in human cancers is largely unexplored." (PMID 38274096, 2023). "Our results indicate that in the SERPINE gene family, SERPINE1 is highly expressed in pan cancer cells, followed by moderate expression of SERPINE2, while SERPINE3 shows low expression." (PMID 40463876, 2025).
SERPINE3 also shares sentences with these, for which no sentence is quoted: glioblastoma (1 paper); neurological disease (1); pancreatic cancer (1); preeclampsia (1); prion disease (1); retinitis pigmentosa (1).